EGFR (epidermal growth factor receptor)
Diseases named in the same sentence as EGFR in open-access papers (continued):
Sharing a sentence is not in itself a finding about the gene and the disease.
non-small cell lung carcinoma (continued). "In one study, higher levels of sPD-1 were associated with longer progression-free survival and OS in 38 patients with non-small cell lung cancer who were being treated with erlotinib, an inhibitor of mutated epidermal growth factor receptor." (PMID 31523394, 2019). "For example, the Cobas® EGFR Mutation Test v2 is used for non-small-cell lung carcinoma since EGFR, a KRAS-activating receptor, is often mutated in this particular cancer." (PMID 31608239, 2019). "In 45 non-small cell lung cancer (NSCLC) patients harboring activating EGFR mutations, cfDNAs were prepared from the plasma samples." (PMID 31217900, 2019). "Most commonly in EGFR-mutant non-small cell lung cancer, secondary resistance mutations on the target kinase domain emerge to diminish the binding affinity of first- and second-generation inhibitors." (PMID 31815659, 2019). "Modest antitumor responses have been reported, with two patients showing PR at 5 mg intermittently and 4 mg continuously, both of whom suffer from EGFR mutation-positive non-small-cell lung cancer with prior EGFR-TKI therapy." (PMID 31731457, 2019). "A similar study which assessed EGFR mutations in cytological samples from patients with non-small cell lung cancer extracted DNA showed a limit of detection of 1%." (PMID 31265477, 2019). "Non-small cell lung cancer (NSCLC) patients with epidermal growth factor receptor (EGFR)-sensitive mutations benefit from epidermal growth factor receptor tyrosine kinase inhibitors (EGFR- TKIs)." (PMID 31777595, 2019). "Intratumoral epidermal growth factor receptor (EGFR) mutational heterogeneity is yet controversial in non-small cell lung cancer (NSCLC) patients." (PMID 31014278, 2019). "The tyrosine kinase epidermal growth factor receptor (EGFR) is frequently mutated in non-small cell lung cancer and has strong interrelations to several metabolic pathways." (PMID 31221963, 2019). "It has been demonstrated that non-small cell lung cancer patients with EGFR mutation had higher objective response rate and longer median progression-free survival time than those with wild type EGFR, no matter detected in tumor tissues or plasma DNA." (PMID 31608233, 2019). "Uncommon mutations account for 10-15% of epidermal growth factor receptor (EGFR) mutations in patients with non-small-cell lung cancer." (PMID 31007929, 2019). "Amplification and mutations of EGFR have been shown to be driving events in many cancers, like non-small cell lung cancer, renal carcinoma, and basal-like breast cancers." (PMID 30895194, 2019). "Non-small-cell lung cancer (NSCLC) with epidermal growth factor receptor (EGFR) mutations has long been regarded as a single entity." (PMID 30857358, 2019). "The current standard work-up of Non Small Cell Lung Cancer (NSCLC) patients includes the search for sensitizing mutations of EGFR gene that allowed identification of patients eligible for treatment with an EGFR tyrosine kinase inhibitor (TKI)." (PMID 31029076, 2019). "EGFR variant detection in cfDNA was the first liquid biopsy test to be approved by the USA Food and Drug Administration, as a companion diagnostic in non-small-cell lung cancer patients." (PMID 30781720, 2019). "To analyze the association of a given genetic profile with clonogenic survival parameters, we chose to analyze EGFR mutation status in non-small cell lung carcinoma (NSCLC); EGFR status is associated with the response of NSCLCs to radiation therapy." (PMID 31349558, 2019). "It has been reported that ABCG2 expression is increased in non-small cell lung cancer lines showing resistance to gefitinib, suggesting that overexpression of this transporter is one of the mechanisms underlying resistance to EGFR TKIs." (PMID 31340525, 2019). "Screening mutations in epidermal growth factor receptor (EGFR) to analyze non-small-cell lung cancer (NSCLC) profile is the criterion to choose the best therapeutic strategy." (PMID 30092812, 2018).
non-small cell lung carcinoma (continued). "Gefitinib, an EGFR tyrosine kinase inhibitor, is used to treat non-small cell lung cancer (NSCLC) patients with activating EGFR mutations." (PMID 29552290, 2018). "Previous studies have shown that haplotypes of EGFR SNPs are associated with non-small cell lung cancer, lung adenocarcinoma, glioma, and glioblastoma." (PMID 30011810, 2018). "Epidermal growth factor receptor (EGFR) mutated non-small cell lung cancer (NSCLC) comprises approximately 15–20% of non-small cell lung cancer in white populations with higher rates in the order of 22–62% reported in Asian populations." (PMID 29561760, 2018). "EGFR itself is mutated in approximately 20% of all non-small-cell lung cancers (NSCLCs), with significantly increased prevalence in patients of Asian ethnicity." (PMID 29192388, 2018). "Erlotinib is approved for the first line treatment of epidermal growth factor receptor (EGFR) mutation-positive non-small cell lung cancer." (PMID 29801465, 2018). "Epidermal growth factor receptor (EGFR) gene mutation is an important driving factor in non-small cell lung cancer (NSCLC)." (PMID 30591099, 2018). "Studies have shown that 70% of EGFR-activating mutations in non-small cell lung carcinoma (NSCLC) are associated with an initial positive response to the EGFR inhibitors gefitinib or erlotinib." (PMID 29455668, 2018). "Treatment of non-small-cell lung cancers (NSCLCs) harboring primary EGFR oncogenic mutations such as L858R and exon 19 deletion delE746_A750 (Del-19) using gefitinib/erlotinib ultimately fails due to the emergence of T790M mutation." (PMID 29568384, 2018). "As exon 19 deletion is the most prevalent EGFR mutation (close to 50%) detected from non-small cell lung cancer (NSCLC) patients, the current study focused on this EGFR mutant and investigated its endocytosis." (PMID 29976202, 2018). "Compared with standard chemotherapy, epidermal growth factor receptor tyrosine kinase inhibitors (EGFR-TKIs) are more effective in patients with advanced non-small-cell lung cancer (NSCLC) harboring EGFR mutations." (PMID 30348116, 2018). "Detection of EGFR sensitizing and p.T790M and p.C797S resistance mutations is particularly important for non-small cell lung cancer (NSCLC) patient therapy management." (PMID 30647840, 2018). "The effect of AQTGTGKT peptide on autophagic flux in H1975 non-small cell lung cancer cells with EGFR mutations (L885R/T790 M) was examined." (PMID 30619741, 2018). "A phase II single arm study enrolled 37 patients with metastatic KRAS- or epidermal growth factor receptor (EGFR)-mutated, treatment-naïve, non-small cell lung cancer." (PMID 29799479, 2018). "Patients with EGFR-mutated non-small-cell lung cancer benefit from EGFR tyrosine kinase inhibitors (TKIs) like erlotinib." (PMID 29899852, 2018). "This companion diagnostic test is used to assess the mutational status of EGFR exon 19 and exon 21 to identify patients with advanced non-small-cell lung cancer (NSCLC) that are eligible for treatment with EGFR tyrosine kinase inhibitors (EGFR-TKI)." (PMID 29747380, 2018). "Non-small cell lung cancer (NSCLC) patients with epidermal growth factor receptor (EGFR) mutation show a high response to EGFR-tyrosine kinase inhibitor (EGFR-TKI)." (PMID 30290647, 2018). "Recently, liquid biopsy that identifies epidermal growth factor receptor (EGFR) gene mutations in non-small cell lung cancers have been approved by FDA." (PMID 29928492, 2018). "The EGFR T790M gatekeeper mutation, which is found in patients with advanced non small cell lung cancer, increases the enzyme’s affinity for ATP43." (PMID 29599515, 2018).
non-small cell lung carcinoma (continued). "Epidermal growth factor receptor (EGFR) tyrosine kinase inhibitors, including gefitinib, are first-line drugs against advanced non-small cell lung cancer with activating EGFR mutations." (PMID 29784046, 2018). "Non-small cell lung cancer (NSCLC) with activating EGFR mutations, especially exon 19 deletions and the L858R point mutation, is particularly responsive to gefitinib and erlotinib." (PMID 29514601, 2018). "To assess our ability to detect subclonal mutations, we examined EGFR T790M in the non-small cell lung carcinoma subset of our dataset, where the mutation would be expected to occur in tyrosine kinase inhibitor resistant subclones." (PMID 29415044, 2018). "None-the-less, such in vitro approaches are capable of generating models with clinically-relevant changes, such as the EGFR T790M mutation in gefitinib-resistant non-small cell lung cancer (NSCLC)." (PMID 29389967, 2018). "The analysis of epidermal growth factor receptor (EGFR) mutations in many patients with advanced non-small-cell lung cancer (aNSCLC) has provided the opportunity for successful treatment with specific, targeted EGFR tyrosine kinase inhibitors." (PMID 29623586, 2018). "This phase I trial was conducted to determine the maximum tolerated dose (MTD) and recommended dose of afatinib for phase II trial in elderly patients with advanced non-small cell lung cancer (NSCLC) harboring epidermal growth factor receptor (EGFR) mutations." (PMID 29423683, 2018). "The clinical features of patients with common single-mutation of epidermal growth factor receptor (EGFR) in non-small cell lung cancer (NSCLC) has been well characterized." (PMID 30172266, 2018). "This study was to explore the value of upfront cranial radiotherapy (RT) in EGFR-mutated non-small cell lung cancer (NSCLC) with BMs compared with EGFR-TKIs alone." (PMID 30619745, 2018). "Epidermal growth factor receptor - tyrosine kinase inhibitor (EGFR-TKI) is the first choice of treatment for advanced non-small cell lung cancer (NSCLC) patients harbouring activating EGFR mutations." (PMID 29662665, 2018). "Apart from it, somatic mutations in the tyrosine-kinase domain of EGFR were identified in 30-50% non-small-cell lung cancers (NSCLCs) patients, among which the TKIs response rate increased to approximately 75%." (PMID 29370817, 2018). "For instance, the Yin and Yang types are associated with genetic mutations in epidermal growth factor receptor (EGFR) in patients with non-small cell lung cancer." (PMID 29867614, 2018). "Targeted therapy of epidermal growth factor receptor tyrosine kinase inhibitor (EGFR-TKIs) has been the standard modality as first-line treatment of advanced EGFR-mutated non-small cell lung cancer (NSCLC)." (PMID 29526178, 2018). "Afatinib, used for the first-line treatment of non-small-cell lung carcinoma (NSCLC) patients with distinct epidermal growth factor receptor (EGFR) mutations, inactivates EGFR by mimicking ATP structure and forming a covalent adduct with EGFR." (PMID 29765556, 2018). "Particularly important hazard of false-negative results obtainment can take place in tumor samples, e.g., in screening for epidermal growth factor receptor (EGFR) mutations in non-small cell lung cancer (NSCLC) patients or in clinical virology." (PMID 29313202, 2018). "The association between the TKIs erlotinib and gefitinib is approved for non-small cell lung cancer (NSCLC) treatment in tumors with specific EGFR mutations (10–15% of Caucasian patients)." (PMID 29770165, 2018). "In fact, the FDA recently approved the first ctDNA test for EGFR mutations in non-small-cell lung cancer (cobas® Mutation Test v2), a first indication of the imminent implementation of ctDNA testing in the clinical setting." (PMID 29747380, 2018). "Genetic analysis of the primary tumor in the present case revealed mutation of the gene encoding EGFR, an event reported to occur in about 10% of cases of non-small cell lung cancer." (PMID 29415746, 2018).
non-small cell lung carcinoma (continued). "Many tumours that originate from epithelial tissues, including SCC, non-small cell lung cancer, gastric, esophageal, colorectal, prostate, renal, bladder, ovarian, and pancreatic cancers are found to be associated with EGFr overexpression." (PMID 29855618, 2018). "Non-small cell lung cancer (NSCLC) patients with EGFR mutations develop acquired resistance to first (erlotinib)- and third (osimertinib)-generation TKIs." (PMID 30323297, 2018). "Roles of CAGE and CAGE-derived peptide in regulating responses to anti-cancer drugs such as erlotinib and osimertinib in non-small cell lung cancer cells with EGFR mutations were revealed for the first time here." (PMID 30619741, 2018). "A total of 251 serial plasma samples from 41 non-small-cell lung cancer patients who carried an activating EGFR mutation were analysed by digital PCR." (PMID 29416630, 2018). "EGFR tyrosine kinase inhibitors (TKI) including gefitinib and erlotinib have demonstrated dramatic efficacy in non-small cell lung cancer (NSCLC) patients with EGFR-activating mutation." (PMID 29717264, 2018). "In a univariate survival analysis for non-small cell lung cancer, a high EGFR mRNA expression was significantly associated with a prolonged progression-free survival." (PMID 30513863, 2018). "Gefitinib, a first-generation EGFR-TKI, greatly improved the prognosis of EGFR gene mutation-positive patients with non-small-cell lung cancer (NSCLC)." (PMID 30445769, 2018). "Erlotinib resistance driven by EGFR mutation (T790M) in non-small cell lung cancer is associated with decreased glutathione level." (PMID 30619741, 2018). "Non-small cell lung cancer (NSCLC) with activating epidermal growth factor receptor (EGFR) mutations, such as exon 19 deletion and the L858R mutation, responds to first and second generation EGFR-tyrosine kinase inhibitors (EGFR-TKIs)." (PMID 30537950, 2018). "This study aims to assess the real-life diagnostic and clinical management and outcome of patients with advanced non-small-cell lung cancer (NSCLC) carrying EGFR mutations in Spain." (PMID 29382302, 2018). "EGFR mutation in non-small cell lung cancer (NSCLC), RET mutation in medullary thyroid carcinoma, ALK translocation and ROS1 translocation in NSCLC and HER2 amplification in breast cancer have been reported and therapies have been established." (PMID 30404198, 2018). "On the other hand, analysis of mRNA expression levels yielded the existence of the “pathways in cancer” and “non-small-cell lung cancer” pathways, which were enriched in EGFR-mutated tumors." (PMID 30404194, 2018). "The discovery of mutations in the epidermal growth factor receptor gene (EGFR) in non-small-cell lung cancer (NSCLC) patients has dramatically changed the treatment strategy." (PMID 30034635, 2018). "Genetic mutation is much complicated after osimertinib treatment in EGFR positive non-small-cell lung cancer." (PMID 29713646, 2018). "The T790M mutation in the epidermal growth factor receptor (EGFR) kinase domain is also responsible for the resistance of non-small cell lung cancer cells to erlotinib and gefitinib." (PMID 29633047, 2018). "In 2011, the American Society of Clinical Oncology advanced clinical guidelines recommending the use of EGFR mutation testing in non-small cell lung cancer (NSCLC) patients in order to consider EGFR tyrosine kinase inhibitors as first line therapy." (PMID 29448963, 2018). "Acquired T790 M mutation is the commonest cause of resistance for advanced non-small cell lung cancer (NSCLC) epidermal growth factor receptor (EGFR) mutant patients who had progressed after first line EGFR TKI (tyrosine kinase inhibitor)." (PMID 29455654, 2018). "Therapeutic strategies for non-small cell lung cancer are based on mutation of epidermal growth factor receptor (EGFR), Kirsten murine sarcoma virus (KRAS), or Anaplastic lymphoma kinase (ALK)." (PMID 29360794, 2018).
non-small cell lung carcinoma (continued). "Afatinib and erlotinib provide significant benefits in progression-free survival compared to gefitinib in first-line treatment of patients with non-small-cell lung cancers harboring EGFR-activating mutations." (PMID 27935868, 2017). "EGFR (exon 19 and exon 21) mutations in patients with advanced non-small cell lung cancer (NSCLC) treated by EGFR-TKIs are associated with a better survival; while KRAS mutations predict a worse prognosis." (PMID 28430611, 2017). "According to the results of a myriad of studies, epidermal growth factor receptor (EGFR) mutations play an important role in selecting treatment options for advanced non-small cell lung cancer (NSCLC) patients." (PMID 28445978, 2017). "Small molecules targeting the EGFR tyrosine kinase domain have been used with some success at treating patients with non-small cell lung cancer driven by activating mutations in the kinase domain." (PMID 28484248, 2017). "A total of 180 serial plasma samples from 18 non-small-cell lung cancer patients who carried an activating EGFR mutation were investigated by digital PCR." (PMID 28947971, 2017). "For example, afatinib (Gilotrif) was approved as an orphan drug in 2013 to treat patients with non-small cell lung cancer with an EGFR positive mutation, a rare variant affecting about 10% of patients." (PMID 28045970, 2017). "As an example, for Tyrosine Kinase Inhibitors (TKIs) targeting the Epidermal Growth Factor Receptor (EGFR), as used in the treatment of non-small cell lung cancer, the underlying reason for this inter-patient variability is best understood." (PMID 28418885, 2017). "EGFR mutations in the tyrosine kinase domain occur in ~10% of Non-small cell lung cancer (NSCLC), and sensitize the patients’ tumors to tyrosine kinase inhibitors (TKI)." (PMID 28591715, 2017). "EGFR-mutated non-small cell lung cancer patients experience relapse within 1-2 years of treatment with EGFR-inhibitors, such as erlotinib." (PMID 28418902, 2017). "We recently studied the mechanism of ERK1/2 activation after EGFR inhibition in non-small cell lung cancer (NSCLC) harboring EGFR mutations." (PMID 28474232, 2017). "The usefulness of the multiplexed genosensing platform was demonstrated by detecting EGFR mutations in saliva samples of patients with non-small cell lung carcinoma (NSCLC)." (PMID 28420103, 2017). "Tyrosine-kinase inhibitors (TKIs) represent the best treatment for advanced non-small cell lung cancer (NSCLC) with common exon 19 deletion or exon 21 epidermal growth factor receptor mutation (EGFRm)." (PMID 28427238, 2017). "For example, activating mutations in the tyrosine kinase domain of the epidermal growth factor receptor (EGFR) have been identified as an oncogenic driver in non-small cell lung cancer (NSCLC) cases." (PMID 28657610, 2017). "Non-small cell lung cancer (NSCLC) harboring common epidermal growth factor receptor (EGFR) gene mutations (exon 19 deletion or exon 21 L858R) respond to EGFR tyrosine kinase inhibitors (EGFR-TKIs)." (PMID 28424065, 2017). "In non-small cell lung cancer (NSCLC) driver mutations of EGFR are positive predictive biomarkers for efficacy of erlotinib and gefitinib." (PMID 28456787, 2017). "Inhibitors of epidermal growth factor receptor (EGFR) such as afatinib, erlotinib, and gefitinib have previously been used to treat non-small cell lung cancer harboring favorable EGFR mutations." (PMID 29228636, 2017). "Other mutations observed in isolated cases included EGFR G721A, which has been shown to respond to Gefinitib or Erlotinib in non-small cell lung cancer and PDGFRA H845Y which has been shown to respond to Imatinib." (PMID 29100278, 2017). "In 2004, it was first reported that a mutation in the epidermal growth factor receptor (EGFR) conferred a clinical response to EGFR tyrosine kinase inhibitors (TKIs) in non-small cell lung cancer (NSCLC)." (PMID 27713133, 2017).